MTOR (mechanistic target of rapamycin kinase)
Diseases named in the same sentence as MTOR in open-access papers (continued):
Sharing a sentence is not in itself a finding about the gene and the disease.
Hepatitis (14 papers, 2015 to 2024). Inflammation of the liver. "Overall, circRNA-100338 is closely associated with poor prognosis of hepatitis B-related HCC by activating mTOR signaling pathway via circRNA-100338/miR-141-3p/RHEB axis." (PMID 31157168, 2019). "In the present study, we showed that ATF3 deficiency aggravated IR-induced liver inflammation by activating of mTOR/p70S6K signaling and increasing TLR4-driven inflammatory responses." (PMID 30185770, 2018). "It inhibits the PI3K/Akt/mTOR pathway that is implicated in EAE and MS, and in an effective fashion prevents the development of a MIF-dependent immunoinflammamtory hepatitis in mice." (PMID 31581595, 2019). "Taken together, these data indicated that ATF3-mediated mTOR/p70S6K/HIF-1α signaling was crucial for T cell differentiation in IR-triggered liver inflammation." (PMID 30185770, 2018). "A relationship between lipid deposition and activation of the PI3K-Akt-mTOR (phosphatidylinositol 3-kinase-protein kinase B-mammalian target of rapamycin) pathway has been confirmed in hepatitis patients." (PMID 25945932, 2015). "We then investigated whether IL-1β also affects mTOR activity in peripheral γδ T cells during CCl4-induced liver inflammation." (PMID 35361750, 2022). "The mTOR pathway is activated in viral hepatitis, including hepatitis B virus (HBV) infection-induced hepatitis." (PMID 34580816, 2021). "Despite the known role of ATF3 in controlling innate inflammatory responses and the involvement of HIF-1α in mTOR signaling, the exact mechanisms by which ATF3 regulates innate immunity and adaptive T cell development in IR-triggered liver inflammation remain largely unknown." (PMID 30185770, 2018).
Hodgkins lymphoma (14 papers, 2013 to 2026). A heterogeneous group of malignant lymphoid neoplasms of B-cell origin characterized histologically by the presence of Hodgkin and Reed-Sternberg (HRS) cells in the vast majority of cases. "In refractory Hodgkin disease and MM, an mTOR inhibitor was introduced in addition to pioglitazone, metronomic low-dose chemotherapy, and COX-2 inhibitor; in Hodgkin lymphoma, a glucocorticoid was used, additionally." (PMID 30424016, 2018). "Among the 4 patients who had PR or SD>12 months, 1 patient with Hodgkin lymphoma had TSC2 loss, a molecular aberration that putatively activates the mTOR pathway." (PMID 27589687, 2016). "Genomic interrogation of Hodgkin lymphoma cell lines has identified dysregulation of the PI3K/mTOR pathway and high AKT phosphorylation." (PMID 24904824, 2014). "The in vitro and in vivo effect of the mTOR inhibitor rapamycin was also examined in human Hodgkin-lymphoma cell lines." (PMID 23693095, 2013). "Hodgkin-lymphoma was characterized by high mTOR activity in 93% of the cases, and Bcl-xL and NF-kappaB expression correlated with this mTOR activity." (PMID 23693095, 2013). "Low mTOR activity was accompanied by complete remission and at least 5-year disease free survival in Hodgkin-lymphoma patients." (PMID 23693095, 2013). "Finally, metronomic low-dose chemotherapy facilitates edited non-oncogene addiction, namely the successful use of repurposed targeted therapies, e.g., mTOR inhibitors, associated with resolution of M-CRAC in r/r Hodgkin’s lymphoma and consecutive cCR." (PMID 38201607, 2023). "As clinically shown, the use of repurposed targeted therapies, e.g., mTOR inhibitors, may contribute to long-term tumor control or cCR in r/r tumor disease, e.g., Hodgkin’s lymphoma or uveal melanoma." (PMID 38201607, 2023). "Another preclinical study showed that, while HDAC inhibition alone led to inhibition of LKB1 and AMP-activated protein kinase and thus increased mTOR activity, the combination of an HDAC inhibitor and an mTOR inhibitor resulted in synergistic tumor cell death in Hodgkin lymphoma cell lines." (PMID 27589687, 2016). "A potential place for off-label mTOR inhibition by everolimus could be relapsed/refractory classical Hodgkin lymphoma, where novel agents are warranted for patients failing PD-1 inhibitors either as monotherapy or in combinations or in the context of metronomic therapy." (PMID 37762410, 2023). "The presence of mTOR activity probably indicates that the inclusion of mTOR inhibition in the therapy of Hodgkin-lymphomas may be feasible and beneficial, especially when standard protocols are ineffective, and it may also allow dose reduction in order to decrease late treatment toxicity." (PMID 23693095, 2013). "Panobinostat was also evaluated in combination with the mTOR inhibitor everolimus in 3 clinical trials in a cohort of B-, T-NHL and Hodgkin lymphoma (HL) patients (NCT00918333, NCT00967044, NCT00978432), in which the best response was an ORR of 33%, and OS and PFS of 35 and 4.2 months, respectively." (PMID 35008680, 2021). "Taken together, Hodgkin-lymphoma is characterized by high mTOR activity, and this high mTOR activity does not exclude good prognosis." (PMID 23693095, 2013). "In particular, the majority of Hodgkin-lymphomas have high mTOR activity (with no mTORC2/Rictor expression)." (PMID 23693095, 2013). "Gatekeeper defective genes, e.g., aberrant expression of PTEN could probably be normalized, as clinically suggested in r/r Hodgkin’s lymphoma, by edited non-oncogene addiction to mTOR." (PMID 38201607, 2023).
laminopathies (14 papers, 2012 to 2024). "Rapamycin, another mTOR regulator, has demonstrated potential in treating laminopathies linked to improvements in adipogenesis, body weight, and reductions in progerin or prelamin A levels." (PMID 39125589, 2024). "Of note, it has been demonstrated that lamin A mutations causing MADA or other progeroid laminopathies are also able to trigger TGFβ 2 signaling with downstream effects on mTOR pathway and osteoclastogenic activity." (PMID 30781376, 2019). "Muscle biopsies from laminopathy patients have shown decreased levels of AMPKα and increased levels of mTOR." (PMID 38834813, 2024). "Nuclear envelope dysregulation and laminopathies are associated with mitogen-activated protein kinase (MAPK) signaling and AKT- mammalian target of rapamycin (mTOR) signaling pathways." (PMID 35734429, 2022). "A similar strategy, i.e., activation of autophagy, has also been used in other models of laminopathies, e.g. in the LmnaH222P/H222P mice, where the mTOR pathway inhibitor temsirolimus enhanced autophagy and improved cardiac function." (PMID 36111332, 2022). "mTOR signaling deregulation is closely related to aging and age-related disorders, among which progeroid laminopathies represent genetically characterized clinical entities with well-defined phenotypes." (PMID 30781376, 2019). "This review explores recent advances on mTOR involvement in progeroid and tissue-specific laminopathies." (PMID 30781376, 2019). "From a basic point of view, the main finding of mTOR studies conducted in models of laminopathies is that functional lamin A/C is required for mTOR-dependent pathways that regulate autophagy and fibrogenic processes." (PMID 30781376, 2019). "Nevertheless, despite this relevant difference in mTOR signaling, in experimental models of all these laminopathies, rapamycin, everolimus, and temsirolimus have been demonstrated to efficiently degrade toxic molecules and/or rescue the phenotype." (PMID 30781376, 2019). "Suppression of cellular senescence by using the mTOR-inhibitor Rapamycin has been discussed as an innovative therapeutic approach in the clinical treatment of laminopathies." (PMID 23804595, 2013). "Considering the critical role of the mTOR pathway in adipogenesis, which is often disrupted in laminopathies, targeting this pathway with rapamycin could significantly enhance adipose tissue formation." (PMID 39125589, 2024). "ATX-2 regulates the mTOR pathway, which is dysregulated in some laminopathies." (PMID 34383046, 2021). "Dysregulated mechanistic target of rapamycin (mTOR) and insulin-like growth factor 1 (IGF1) signaling, impaired nutrient sensing, and autophagy are implicated in the pathogenesis of progeroid syndromes, laminopathies, as well as aging in the general population." (PMID 35531366, 2022). "Indeed, using a KO mouse model for LMNA, Kennedy’s group described that the absence of lamin A/C activated the mTOR signaling axis associated with laminopathy phenotypes, namely, an impaired cardiac function and skeletal muscle dystrophy." (PMID 32842478, 2020). "However, recent findings showing that other mTOR dependent mechanisms such as nutrient intake and energy expenditure are affected in laminopathies suggest a more complex therapeutic strategy aimed at rescuing good metabolic conditions while reducing levels of mutated lamins." (PMID 30781376, 2019). "Recent advances on pathological mechanisms involved in progeroid or tissue specific laminopathies, report the activation of the AKT/mTOR pathway, ultimately impairing the autophagic activity." (PMID 32012908, 2020). "Our findings are consistent with studies in mouse laminopathy models in which rapamycin and temsirolimus had beneficial effects on heart and skeletal muscle through inhibition of AKT/mTOR signaling." (PMID 29575479, 2018).
laminopathies (continued). "Several preclinical therapeutic strategies have shown promise in laminopathies, including p38α mitogen-activated protein kinase (MAPK) inhibitors, mammalian target of rapamycin (mTOR) inhibitors and nicotinamide riboside, a precursor to nicotinamide adenine dinucleotide (NAD+)." (PMID 39501809, 2024). "Importantly, treatment with rapamycin, which is a specific mTOR-inhibitor, contributed to an improvement of LMNA–/– mice phenotypes and an elevation of survival, showing that mTOR activation might mediate phenotypes involved in laminopathy diseases." (PMID 32842478, 2020).
malignant pleural mesothelioma (14 papers, 2014 to 2025). A malignant neoplasm that arises from mesothelial cells in the pleura and shows a diffuse growth pattern. "AKT activation has been demonstrated in malignant pleural mesothelioma specimens and PI3K/mTOR inhibitors significantly suppressed malignant pleural mesothelioma cell growth." (PMID 28159921, 2017). "However, results of a phase II study in advanced malignant pleural mesothelioma were disappointing as the single agent everolimus had limited clinical activity, probably because of the activation of AKT negative-feedback after mTOR inhibition, as demonstrated in vitro." (PMID 31752449, 2019).
metastatic melanoma (14 papers, 2012 to 2025). A melanoma that has spread from its primary site to another anatomic site. "The second is a single-arm, open-labeled and single-centered study of everolimus in selective patients with metastatic melanoma and mutations (Kinase domain) of mTOR." (PMID 32850962, 2020). "The transition from RGP to VGP has been reported to be associated with Akt activation, where heightened Akt/mTOR activities has been reported in about 70% of metastatic melanoma." (PMID 31370278, 2019). "Interestingly, analyzing 31 candidate genes existing in either the PI3K or MAPK pathway in 105 metastatic melanoma patients, the researchers found two novel nonsynonymous mutations (R2443∗ and L552F) in MTOR gene." (PMID 32850962, 2020). "Some synthetic small molecule compounds have been shown to mechanistically target the PI3K/Akt/mTOR and associated RAS/RAF/MEK/ERK or MAPK signaling pathway as promising treatments against metastatic melanoma." (PMID 31370278, 2019). "Overall, in metastatic melanoma, the PI3K pathway is altered by somatic mutations in a wide array of genes including PIK3CA, MTOR, PIK3R1, PIK3R5, and IRS4." (PMID 22912864, 2012). "The most profound inhibition was, however, noticed in the case of applications of the combination of mTOR inhibitor—everolimus, with PI3K kinase inhibitor—LY294002, which reduced proliferation of Lu1205 metastatic melanoma cells by 62% (p < 0.0005) in." (PMID 29214525, 2017). "The expression of components of the renin–angiotensin system by phenotypic CSCs in metastatic melanoma, coupled with the interactions between the renin–angiotensin system and the overactive Ras/RAF/MAPK/ERK and PI3K/AKT/mTOR pathways, present vast therapeutic possibilities." (PMID 39941158, 2025). "Moreover, to validate the differential enrichment of the mTOR pathway, we analyzed the single-cell transcriptomes of CD8+ TILs from a new cohort of metastatic melanoma patients collected prior to anti-PD-1 immunotherapy." (PMID 38023136, 2023). "Importantly, the lack of change observed with mTOR inhibition alone is consistent with the lack of clinical activity seen with Temsirolimus alone in metastatic melanoma and may provide some insight into the lack of clinical impact with this agent alone." (PMID 24047116, 2013).
muscle atrophy (14 papers, 2015 to 2025). The loss of muscle tissue due to inactivity or disease. "Western blotting and RT-PCR were utilized to analyze MyoD, Myogenin, Atrogin-1, and MuRF1 protein and gene expression in a muscle atrophy model, as well as the Akt/mTOR and FoxO3α pathways." (PMID 39770504, 2024). "We also demonstrated that valeric acid stimulates type IIb myofiber growth by activating the Akt/mTOR pathway via G protein-coupled receptor 43 and ameliorates dexamethasone-induced muscle atrophy." (PMID 37039469, 2023). "In line with this notion, other downstream targets of mTOR signaling, i.e. 4EBP1 and S6, also display reduced phosphorylation levels reflective of decreased mTORC1 activity in the initial phases of muscle atrophy." (PMID 29720191, 2018). "As a critical nutrient/energy sensor, mTOR activation via AGEs-RAGE signaling suppresses protein synthesis by reducing the phosphorylation of mTOR, p70s6k, and 4E-BP1, ultimately causing skeletal muscle atrophy in mice." (PMID 41551513, 2025). "Specifically, the decreased phosphorylation of AKT (Ser‐473), FOXO3A (Ser‐253), mTOR, P70S6K, and 4EBP1 in Den‐induced muscle atrophy were also attenuated after knocking down circDdb1." (PMID 39412095, 2024). "Muscle atrophy is thought to primarily result from a decreased protein synthesis based on a reduced activation of the IGF1-Akt-mTOR and the FAK-Akt-mTOR pathways." (PMID 30740059, 2019).
overgrowth syndrome (14 papers, 2017 to 2025). A group of syndromes caused by genetic birth defects that may lead to the development of malignancies. "Since constitutive activation of the PI3K/AKT/mTOR pathway is a major cause of vascular anomalies and overgrowth syndromes, the use of mTOR inhibitors, such as Sirolimus, appeared as a good therapeutic strategy." (PMID 34568242, 2021). "Somatic activating mutations in the PI3K/AKT/mTOR pathway are among the most common mutations identified in cancer and have been shown to cause a spectrum of overgrowth syndromes including PIK3CA-Related Overgrowth Spectrum, Proteus syndrome, and brain overgrowth conditions." (PMID 40406354, 2025). "Besides cancer and overgrowth syndromes, alterations in the PI3K/AKT/mTOR pathway are major drivers of abnormal proliferation." (PMID 28353628, 2017).
pancreatic adenocarcinoma (14 papers, 2018 to 2026). "In conclusion, dual targeting of the Aurora A kinase and mTOR resulted in marginal clinical benefit in a population of patients with refractory solid tumors, including a cohort of patients with pancreatic adenocarcinoma." (PMID 38672538, 2024). "Moreover, the combined activation of PP2A and inhibition of mTOR can synergistically suppress growth of pancreatic adenocarcinoma." (PMID 32905878, 2020). "Preclinical studies, specifically in pituitary and pancreatic adenocarcinoma cells, have demonstrated synergistic effects through dual inhibition of the PI3K/AKT/mTOR pathway." (PMID 39996718, 2025). "In pancreatic adenocarcinoma, the combination of UCP2 inhibitor genipin and mTOR inhibitor everolimus results in synergistic suppression of cancer cell growth and induction of cell apoptosis." (PMID 38217303, 2024).
pancreatitis (14 papers, 2016 to 2026). Inflammation of the pancreas. "Intriguingly, Reg4 deficiency leads to an increase in the activation of AMPK, suggesting that AMPK/mTOR signaling may be involved in Reg4 deficiency-mediated autophagic inhibition during pancreatitis." (PMID 38769308, 2024). "The 6‐h time point after pancreatitis induction showed the highest number of signaling terms/pathways, represented by the mTOR, quorum sensing, JAK/STAT, adherens junctions, cell adhesion molecules, and phospholipase D pathways." (PMID 41316847, 2026). "Especially, serum levels of amylase and lipase were greatly reduced, suggesting that mTOR inhibition confers significant suppression of the ‘waterfall effect’ in pancreatitis." (PMID 38358010, 2024). "For example, in a model of traumatic pancreatitis, the effect of the biological agent ucMSC-Ex (umbilical cord mesenchymal stem cell exosomes) attenuates pancreatic damage, activating autophagy in pancreatic acinar cells by inhibiting mTOR." (PMID 40243995, 2025). "WB analysis herein indicated that phosphorylated-AMPK (p-AMPK) increased and phosphorylated-mTOR (p-mTOR) decreased, with concomitantly reduced autophagy in the pancreases of Reg4−/− mice during pancreatitis, but these alterations were circumvented by rReg4 administration." (PMID 38769308, 2024). "We warn clinicians to have a high degree of suspicion for AP in KT transplant patients and possibly avoid mTOR inhibitors in patients who had previous episodes of subclinical pancreatitis, since it may represent a precipitating factor." (PMID 27793122, 2016). "In order to analyse the influence of ucMSC‐Ex on the expression of mTOR on pancreatitis, we used rapamycin and MHY1485 to regulate mTOR." (PMID 38358010, 2024). "The regulatory effects of S1P signaling on pancreatitis predominantly involve NF-κB, STAT3 phosphorylation, PERK/TXNIP/NLRP3, RhoA/ROCK, and AMPK/mTOR pathways as well as IFN-γ and TGF-β1." (PMID 39519028, 2024). "In order to evaluate the ability of lanreotide to overcome tumor cell resistance to mTOR inhibitors, we generated an everolimus-resistant BON-1 pancreatic NET cell line." (PMID 32766136, 2020). "During this period, 10 enriched pathways were observed, including mTOR, quorum sensing, JAK/STAT, adherens junctions, cell adhesion molecules, and phospholipase D. The cell adhesion molecules pathway is enriched from 1 h after pancreatitis induction up to 6 h." (PMID 41316847, 2026). "It was also reported that Cycas species exert their antioxidant effect through inhibition of microRNA216a, which is a key activator for the PI3K/AKT/mTOR pathway, resulting in a reduced level of MDA and increased level of GPX in a rat model of brain damage and pancreatitis." (PMID 39519654, 2024).